CDK18 (cyclin dependent kinase 18)
Description:
May play a role in signal transduction cascades in terminally differentiated cells.
Synonyms: PCTAIRE3; PCTK3; PCTAIRE
Tractability: Small molecule: a drug acting on it is in phase 2 or 3 trials; a high-quality ligand is known; it belongs to a druggable protein family. PROTAC: it is named in the literature on targeted protein degradation; ubiquitination databases record sites on it; a small molecule that binds it is known.
Target class: Protein Kinase; Enzyme; Kinase; CMGC protein kinase group; CMGC protein kinase CDK family; CMGC protein kinase PCTAIRE
Chemical probes: JA397 (high quality)
Gene: Protein-coding gene on chromosome 1 (205,504,561 to 205,532,976, forward strand). Ensembl gene ENSG00000117266.
Subcellular location (Human Protein Atlas): Actin filaments; Cytosol; Basal body; Mitotic spindle; Primary cilium
Gene Ontology:
Molecular function: protein binding; cyclin-dependent protein serine/threonine kinase activity; ATP binding; protein kinase activity; protein serine kinase activity
Biological process: positive regulation of myelination; regulation of cell cycle phase transition
Cellular component: mitochondrion; cyclin-dependent protein kinase holoenzyme complex; cytoplasm
Genetic constraint (gnomAD): Loss-of-function variants: 48 observed, 56.47 expected, observed/expected ratio (o/e) 0.85, 90% interval 0.67 to 1.08. The upper end of that interval is the gene's LOEUF score, 1.08, which puts it in group 4 of 6, group 1 being the genes least tolerant of losing a copy. Missense variants: 578 observed, 603.22 expected, observed/expected ratio (o/e) 0.96, 90% interval 0.89 to 1.03. Synonymous variants: 230 observed, 240.99 expected, observed/expected ratio (o/e) 0.95, 90% interval 0.86 to 1.07.
Homologues: Orthologues: chimpanzee CDK18 (99% identical), macaque CDK18 (99% identical), dog CDK18 (94% identical), guinea pig CDK18 (93% identical), pig CDK18 (93% identical), rat Cdk18 (88% identical), mouse Cdk18 (87% identical), zebrafish cdk18 (78% identical), tropical clawed frog cdk18 (76% identical), rabbit CDK18 (62% identical). Paralogues in human: CDK17 (70% identical), CDK16 (64% identical), CDK14 (45% identical), CDK15 (39% identical), CDK13 (35% identical), CDK5 (35% identical), CDK11B (34% identical), CDK12 (34% identical), CDK11A (34% identical), CDK2 (33% identical), CDK1 (32% identical), CDK3 (32% identical), and 14 more.